AASDHPPT (aminoadipate-semialdehyde dehydrogenase-phosphopantetheinyl transferase)
Description:
Catalyzes the post-translational modification of target proteins by phosphopantetheine. Can transfer the 4'-phosphopantetheine moiety from coenzyme A, regardless of whether the CoA is presented in the free thiol form or as an acetyl thioester, to a serine residue of a broad range of acceptors including the acyl carrier domain of FASN.
Synonyms: AASD-PPT; CGI-80; LYS5; ACPS; LYS2
Tractability: Small molecule: a structure with a bound ligand is known. PROTAC: ubiquitination databases record sites on it; its protein half-life has been measured.
Target class: Enzyme; Transferase
Gene: Protein-coding gene on chromosome 11 (106,075,501 to 106,098,708, forward strand). Ensembl gene ENSG00000149313.
Subcellular location: Cytoplasm, cytosol
Pathways (Reactome):
Metabolism: Vitamin B5 (pantothenate) metabolism
Gene Ontology:
Molecular function: holo-[acyl-carrier-protein] synthase activity; magnesium ion binding; protein binding
Biological process: 10-formyltetrahydrofolate catabolic process; protein maturation; pantothenate metabolic process
Cellular component: cytosol; extracellular exosome
Genetic constraint (gnomAD): Loss-of-function variants: 15 observed, 30.65 expected, observed/expected ratio (o/e) 0.49, 90% interval 0.33 to 0.75. The upper end of that interval is the gene's LOEUF score, 0.75, which puts it in group 3 of 6, group 1 being the genes least tolerant of losing a copy. Missense variants: 331 observed, 353.29 expected, observed/expected ratio (o/e) 0.94, 90% interval 0.86 to 1.03. Synonymous variants: 103 observed, 120.32 expected, observed/expected ratio (o/e) 0.86, 90% interval 0.73 to 1.01.
Homologues: Orthologues: chimpanzee AASDHPPT (100% identical), macaque AASDHPPT (99% identical), guinea pig AASDHPPT (96% identical), dog AASDHPPT (92% identical), mouse Aasdhppt (91% identical), rat Aasdhppt (91% identical), pig AASDHPPT (81% identical), rabbit AASDHPPT (64% identical), tropical clawed frog aasdhppt (61% identical), zebrafish aasdhppt (54% identical), Drosophila melanogaster CG32099 (29% identical), Caenorhabditis elegans T04G9.4 (28% identical), and 1 more.
Diseases named in the same sentence as AASDHPPT in open-access papers:
AASDHPPT is named in the same sentence as 10 diseases in open-access papers, as found by Europe PMC text mining. Sharing a sentence is not in itself a finding about the gene and the disease. The quoted sentences say what the papers report.
cancer (1 paper, 2023). A tumor composed of atypical neoplastic, often pleomorphic cells that invade other tissues. "Initially, we explored the correlation between CNV and mRNA expression in 14 RMS model-associated genes in 33 kinds of tumors and revealed that CHMP7 expression was significantly modulated by CNV in almost all cancers, followed by SEPHS1 and AASDHPPT." (PMID 37124622, 2023).
genetic disease (1 paper, 2026). "We searched the ClinVar database and identified several missense variants of uncertain significance (VUS) in AASDHPPT that were associated with suspected genetic disease." (PMID 41061852, 2026).
AASDHPPT also shares sentences with these, for which no sentence is quoted: infection (3 papers); co-infection (1); colon cancer (1); glioma (1); iron deficiency (1); melanoma (1); ovarian carcinoma (1); tuberculosis (1).